IL10 (interleukin 10)
Diseases named in the same sentence as IL10 in open-access papers (continued):
Sharing a sentence is not in itself a finding about the gene and the disease.
tumor (continued). "To test this hypothesis, we first compared the abilities of several immune modulators to lower production of the immunosuppressive cytokine, IL-10, by tumor-derived Tregs." (PMID 37928524, 2023). "However, regulatory T cells that produce cytokines, such as TGF-β and IL-10, are recognized as components that promote tumor growth." (PMID 38137433, 2023). "We assessed the effects of molecules and their complexes on cells’ viability, parameters of apoptosis induction, IL-10 secretion and expression of surface molecules, characterizing interactions of tumor cells with the immune microenvironment (PD-L1, TIM-3, CD47)." (PMID 36986829, 2023). "Moreover, IL-10 enhances the suppressive effects of tumor cell supernatants on IFN-α secretion from pDCs78." (PMID 37817484, 2023). "The second type is immunosuppressive tumors, which have a moderate infiltration of T cells but a large number of immunosuppressive factors (transforming growth factor β [TGF-β], VEGFA, and IL-10), and a large number of immunosuppressive cells (MDSCs, Treg cells, etc.)are present in the tumor tissue." (PMID 37055849, 2023). "By blocking the effects of inhibitory cytokines like IL-10, ruxolitinib may promote NFκB-signaling and perhaps even tumor progression." (PMID 37114129, 2023). "Conversely, tumours can also produce tumour necrosis factor-alpha, interferon-gamma, interleukin-10 and interleukin-12, which may decrease lymphocytic activity as they are immunosuppressive molecules." (PMID 37046847, 2023). "A two-way circuitry is built in the HGOS microenvironment, because tumor cells secrete trophic factors for MDSCs as IL-1, IL-6, IL-10, TNF-α (tumor necrosis factor-α) and MCP-1 (monocyte chemoattractant protein 1), receiving as a cashback an immune niche favorable to their growth." (PMID 36614241, 2023). "In addition to the usual inducers, protein kinase N2 (PKN2) protein kinase is equally capable of inducing DUSP6 in tumor-associated macrophages, reducing ERK activity and the anti-inflammatory cytokines IL-4 and IL-10." (PMID 38139370, 2023). "Simultaneously, the IL-10 produced by TAMs activates regulatory T (Treg) cells, leading to the inhibition of macrophage response to LPS and consequently suppressing the immune response, thereby promoting tumor progression." (PMID 37968714, 2023). "Interestingly, iTregs also produce both IL10 and TGFβ1, are found in solid tumour infiltrates and are indicative of a poor anti-tumour response during cancer progression." (PMID 36973425, 2023). "Besides, in the MMTV-PyMT tumor model, blocking IL-10 signaling by anti-IL-10 receptor antibody enhanced treatment response to carboplatin and paclitaxel." (PMID 38008741, 2023). "Keratinocytes also produce IL-10 to create a tumor-supportive chronic inflammatory environment." (PMID 37508372, 2023). "In addition, the group with WT1-332-specific IL-10 released from PBMCs tended to have a lower completion rate and a higher rate of tumor progression." (PMID 36672344, 2023). "Furthermore, mast cells indirectly release IL-10 and tumour growth factor by interacting with myeloid-derived suppressor cells and regulatory T cells, enhancing their immunosuppressive activity." (PMID 37928785, 2023). "Through the inhibitory action of IL-10 on the immune system, tumor growth is facilitated." (PMID 37371050, 2023). "Therefore, observably IL6 and IL10 act in a pro-tumor immunosuppressive loop in TME where both M2 and CSCs secrete them, supporting the growth of one another." (PMID 38035101, 2023). "In this study we found that CD4 produced a large amount of IL-10 in TLS of the tumor which suggests that CD4 may regulate B cell IgG4 production by up regulating the level of IL-10." (PMID 36891293, 2023). "Indeed, the IL-10 production by the tumor is able to counteract the tumoricidal effect of the pro-inflammatory cytokine IL-6 secreted by macrophages by inducing, via SOCS3, negative feedback on the IL-6 signaling." (PMID 37835437, 2023).
tumor (continued). "Thus, recent investigations have described a Breg population composed of IL-10+ B cells that coexist with regulatory T cells (Tregs) in human breast and ovarian cancers, which favor the development of metastasis and promote tumor growth." (PMID 37622111, 2023). "IL-10 inhibition can be an effective tumor treatment strategy." (PMID 36891319, 2023). "Additionally, TAMs induced the secretion of the anti-inflammatory cytokines TGF-β and IL-10, which stimulated tumor growth." (PMID 37142967, 2023). "M2 macrophages are associated with high expression of IL-10, IL-1β and vascular endothelial growth factor (VEGF) in vivo, and form a beneficial survival environment for tumor cells by suppressing immunity and promoting tumor angiogenesis, invasion and distant metastasis." (PMID 37901223, 2023). "We analyzed whether there were changes in the production of IL-10 and IL-12 in the DCs of tumor tissues and TdLNs in relation to combination therapy." (PMID 35794399, 2023). "These cytokines, including TNFα and IL‐10, may shift the threshold of immune subsets activation within the tumor micro‐environment, thereby resulting in augmented adaptive immune responses." (PMID 37737046, 2023). "MDSCs can be induced in vitro by various tumour-derived substances, including prostaglandin E2, interleukin-6, interleukin-10, interleukin-1, transforming growth factor (TGF), stem cell factor (SCF), and pro-angiogenic factors, including vascular endothelial growth factor (VEGF)." (PMID 38104117, 2023). "The specific evaluation of the IL-10 and IL-6 expression levels, both in macrophages and in tumor cells, revealed an opposite trend in the IL-10/IL-6 ratio in the co-culture of macrophages with the MG-63 cell line compared with co-culture with HOS and 143B cells following mifamurtide administration." (PMID 37835437, 2023). "We hypothesize that this change in the ratio of IFNγ to IL10 in the cytotoxic Tr1-like cells plays a key role in their anti-tumor role in the presence of PD1 blockade." (PMID 37654482, 2023). "Expression of LILRB2 on tumours correlates with higher levels of IL-10." (PMID 38022598, 2023). "Conversely, IL-10 promoted the growth of tumor B cells through an autocrine loop." (PMID 36680271, 2023). "They release suppressive cytokines such as IL-10 and promote immunosuppression within the tumor." (PMID 38263981, 2023). "As a well-known immunosuppressive cytokine, IL-10 may also engage in promoting tumor progression after incomplete LITs." (PMID 36831664, 2023). "Furthermore, APS can upregulate the levels of IL-2 in the serum of 4T1 tumor-bearing mice and H22 hepatoma mice and promote the levels of IL-4 and IL-10 in the serum of tumor-bearing mice treated with a focused ultrasound." (PMID 37959774, 2023). "The M2d macrophages play an important role in tumor progression and are characterized by increased IL-10 and VEGF secretion and decreased expression of IL-12 and TNF-α, however, the specific mechanism underlying programming the M2d macrophages remains controversial." (PMID 36845095, 2023). "IL10 can promote tumor cell proliferation and metastasis via immunosuppression." (PMID 36661524, 2023). "However, as tumors progress, the tumor microenvironment becomes enriched with cytokines, such as IL-4, IL-10, TGF-β, M-CSF, and prostaglandin E2, promoting the polarization of macrophages towards the M2 phenotype." (PMID 37689664, 2023). "Furthermore, we co-cultured microglia with tumor cells and measured the cytokines IL-10 and IL-6, characteristic for M2 and M1, respectively, upon SKI-II administration." (PMID 36672428, 2023). "In fact, recombinant PEGylated IL-10 inhibited tumor cell growth in mice." (PMID 37998326, 2023). "In a mouse model, subtotal tumor resection was shown to increase levels of IL-1, IL-6, and IL-10." (PMID 37568571, 2023). "In addition, the SLRP decorin also exhibited anti-tumorigenic properties by downregulating the release of IL-10 thereby inhibiting tumor growth." (PMID 37730606, 2023).
tumor (continued). "Using our protocol, CAR T cells, regardless of which ICD was included, that were repeatedly stimulated with tumor cells secreted significantly lower levels of proinflammatory cytokines and upregulated the expression of IL-10 and the exhaustion-related transcription factor TOX." (PMID 37932456, 2023). "Furthermore, immunosuppressive cytokines such as TGF-β1 and IL-10 in tumor tissues were decreased by resveratrol, whereas antitumor cytokines TNF-α and IFN-γ were increased." (PMID 37560476, 2023). "TAMs stimulated by the hypermutated environment of the tumor are often polarized to the M2 subtype and participate in tumor immune escape by producing cytokines such as IL-10, PGE2, and TGFβ, and are closely related to poor prognosis of many cancers and the occurrence of drug resistance." (PMID 37426654, 2023). "IL-10 promotes immunosuppression, angiogenesis, tumor growth, and metastasis." (PMID 37275901, 2023). "Treg is generally identified as FoxP3 + lymphocytes, induced forms of thought to contribute to tumor-specific T-cell tolerance and suppress autoimmunity and antitumor immunity through secretion of inhibitory cytokines such as IL-10 and transforming growth factor-beta (TGF-β)." (PMID 37563607, 2023). "Therefore, we assumed that other tumor suppressor factors are present in the MC38 tumor microenvironment, such as IL-10, which adversely affects the direction and effectiveness of applied DCs." (PMID 37033926, 2023). "Moreover, M2 macrophages presented in the immune microenvironment abundantly of C2 can secrete immunosuppressive factors such as TGF-β and IL-10, which weaken the effects of T-cells, NK cells and other tumor-killing cells." (PMID 37091788, 2023). "The level of IL-10 expression is closely related to tumour immunosuppression." (PMID 37742025, 2023). "The IL10 response leads to the expression of anti-inflammatory mediators that block various inflammatory pathways, therefore has prominent role in regulating intestinal inflammation, tumor immunosuppression, viral infection, allergic reactions." (PMID 36835413, 2023). "Patients consuming the KD with chemotherapy were found to have reduced tumor sizes by an additional 21mm, lower cancer staging, increased anti-tumorigenic factors of IL-10, reduced factors that promote angiogenesis such as TNF-alpha, insulin, and IGF-1, and a higher survival rate." (PMID 37937022, 2023). "Moreover, cancer-associated fibroblasts (CAFs) from breast tissue can produce IL-10 that disrupts the cytokine balance to stimulate tumor growth by initiating angiogenesis." (PMID 37238871, 2023). "IL-10 is an immunosuppressive cytokine, which can promote T-cell exhaustion by regulating the expression of inhibitory receptors on TILs, thereby limiting effective anti-tumor immunity." (PMID 36816967, 2023). "These pathological cells exert an immunosuppressive effect due to the overproduction of interleukin-10 (IL-10), transforming growth factor-β (TGFβ), arginase and nitric oxide (iNOS) in the tumor microenvironment, and also promote tumor growth by expressing T cell-inhibiting cell surface receptors." (PMID 37904131, 2023). "Elevated levels of IL-10 were reported to promote tumor development." (PMID 37110586, 2023). "Lin28B increased IL-6 and IL-10 production, which could convert infiltrated neutrophils from tumor-suppressive to tumor-promoting." (PMID 37496019, 2023). "Furthermore, treatment of syngeneic mouse tumors with recombinant human IL-10 induced CD8+ T-cell-dependent tumor rejection." (PMID 37629156, 2023). "Tumor development and progression is accompanied with chronic cellular stress, which may be a reason for IL-10 secretion by malignant cells." (PMID 36830840, 2023). "Malignant cells, including tumor cells and M2-type tumor-associated macrophages (TAMs), contribute to the construction of the TME by secreting substances like VEGF, platelet-derived growth factor (PDGF) and IL-10." (PMID 37654704, 2023).
tumor (continued). "Gal-1 can interact with TCR and CD45, affect CD45 phosphatase activity and the downstream signaling pathway of effector T cells, and selectively promote Treg amplification and secretion of IL-10, eventually leading to T-cell exhaustion and promoting tumor cell immune escape." (PMID 36793048, 2023). "For instance, certain intestinal bacteria may activate the NF-κB or STAT3 pathway to induce the production of cytokines such as IL-10 and IL-17, which are believed to promote tumor cell proliferation and metastasis." (PMID 37711628, 2023). "While IL‐10 expression was not significantly different, there was a tendency towards lower expression in Cyp11b1‐deficient tumours (P = 0.0837)." (PMID 36861295, 2023). "Furthermore, IL33 expression levels were positively correlated with those of Th1 cytokines (IL2 and IFNG) and Th2 cytokines (IL4 and IL10) in 41 tumor tissues." (PMID 37056569, 2023). "However, recent studies have reported that B cells dampen the tumour immune response by producing certain cytokines, such as IL-10, IL-35, TGF-β and even gamma-aminobutyric acid (GABA)." (PMID 36890557, 2023). "IL-10, IL-18, and inflammasome expression levels were assessed in the tumor tissues." (PMID 37528154, 2023). "M2‐TAMs that secrete CCL17 and IL‐10 have been shown to promote tumor growth." (PMID 35838343, 2023). "The injection of iNKT cell agonists into mice with tumors led to a significant reduction in the frequency of MDSCs and the removal of the immunosuppressive factor IL-10 from MDSCs, leading to an increase in the frequency of tumor-specific T cells as well as inhibiting tumor progression." (PMID 37857728, 2023). "Furthermore, the expression or activity of MDSCs-associated molecules (ARG1, CYBB, iNOS, IL-10, NCF4, and TGF-β2) were significantly decreased from GPR84−/− mice in both LLC and B16F0 tumor models." (PMID 37105980, 2023). "Consequently, conditional deletion of Il10 within T cells augments anti-tumor immunity upon Treg cell-depletion in mice, and antibody blockade of IL-10 signaling synergizes with Treg cell depletion to overcome treatment resistance." (PMID 38100544, 2023). "Pro-inflammatory cytokines such as IL-1β, IL-8, IL-12, TNF-α, IFN-γ, and anti-inflammatory cytokines like IL-4 and IL-10 have dual functions, activating anti-tumorigenic actions of T cells while also participating in tumor malignant transformation, growth, invasion, and metastasis." (PMID 38022654, 2023). "MDSCs and tumor-associated macrophages (TAMs) in HCC can suppress NK cell cytotoxicity through NKp30 on NK cells, and Tregs can impair the immune responses of NK cells by releasing immunosuppressive cytokines IL-8, IL-10, and TGF-β." (PMID 36773210, 2023). "The occurrence of this phenomenon in cancer disease may lead to the escape of tumor cells from immune surveillance, and the increased concentration of IL-10 in the serum of cancer patients is correlated with an unfavorable prognosis." (PMID 37033926, 2023). "Additionally, HCMV-infected tumor cells produce immunosuppressive cytokines such as IL-10 to escape the immune responses and counteract the pro-inflammatory cytokines production." (PMID 37340387, 2023). "Furthermore, a variety of soluble factors like TGF-β, IL–10 etc are released by tumor/stromal cells inhibit T-cell activation and dendritic function while promoting stromal remodelling and angiogenesis." (PMID 37056346, 2023). "For example, premalignant lesions and NSCLC can downregulate interferon signaling to avoid tumor-suppressive inflammation, or secrete inhibitory cytokines like IL-10 that remodel the TME to attract tumor-supporting cells like M2-type macrophages and regulatory T cells." (PMID 37958404, 2023). "M-MDSCs can further differentiate into tumour-associated macrophages (TAMs) which have an immunosuppressive M2 phenotype that secrete IL-10, express PD-1 and contribute to tumour angiogenesis, and appears to depend on S100A9 expression and signalling acting via C/EBPbeta." (PMID 37033972, 2023).
tumor (continued). "Treg cells secrete TGF-β and IL-10, which further interferes with anti-tumor immunity." (PMID 36971124, 2023). "Bregs in murine tumor models and cancer patients have been shown to attenuate antitumor immunity by secreting anti-inflammatory mediators (e.g., IL-10, TGF-β, and IL-35) by suppressing T-cell immune responses and to promote tumor progression by promoting Treg production." (PMID 37519793, 2023). "However, high levels of the tumor-infiltrating B cells, especially regulatory B cells (Bregs), drive tumor progression by producing immunosuppressive cytokines, such as IL10 and TGF-β, which are found to be simultaneously expressed with FANCI." (PMID 37324186, 2023). "Notably, TERT deficiency and dysfunctional telomeres reduced peripheral IL6 and TNF levels, as well as expression of inflammation and tumor immunosuppression markers Tnf, Ifng, IL10 and PD-1 upon LLC challenge." (PMID 37085672, 2023). "In addition to inhibiting CD8+ T cells directly, IL10 activates STAT3 signaling in tumor cells, which promotes cell proliferation correlating with enhanced OC growth and chemoresistance." (PMID 38264664, 2023). "Additionally, the sialoglycan on the surface of tumor cells impedes the secretion of TNF-α by Siglec-9 positive macrophages while promoting the secretion of IL-10." (PMID 37645415, 2023). "IL-10 has been reported both for its anti-tumor and pro-tumor functions." (PMID 36830840, 2023). "In addition, TAMs suppress the antitumor response by producing IL-10 and prostaglandin E2 and promote tumor cell invasion and metastasis by producing MMP-2 and MMP-9." (PMID 37046639, 2023). "In addition, IL-10 mRNA expression in both TRAIL-R KO tumor tissues was disrupted in the 8 mg/kg smTRAIL group." (PMID 37605148, 2023). "Tregs also secrete TGF-β and IL-10 that further inhibit anti-tumor CTL." (PMID 37568390, 2023). "Interestingly, ILC3s were mainly identified in the early stages and during tumor progression transdifferentiated into immunosuppressive ILCs, producing IL-10 to promote tumor progression." (PMID 37514187, 2023). "Similarly, the inhibitory immune microenvironment within the tumor shows up-regulation of the IL-10 factor, which is involved in inflammation and immunosuppression and promotes immune evasion." (PMID 37318594, 2023). "Our data therefore suggest a mechanism by which Tox-induced IL-10 production by tumor-infiltrating T cells and may act to maintain T cell effector activity." (PMID 38054003, 2023). "Tumors stimulate Bregs to secrete IL10 via CD40L signals or tumor-derived exosome." (PMID 37568713, 2023). "Release of IL-10 and IL-12(p70) in both tumor lysates and blood plasma was below detection level." (PMID 37465665, 2023). "In the advanced stage of tumor progression and metastasis, TAMs usually favor the M2 phenotype, which is characterized by low expression of iNOS and IL-12, and high expression of CD206, Arg-1 and IL-10, promoting tissue repair and angiogenesis in favor of tumor progression." (PMID 37127625, 2023). "Based on the results of blood tests and immune organ indices, we hypothesized that WCP could achieve anti-cancer effects by enhancing immunity in mice, so we measured IL-10 in serum, which is closely related to tumor development." (PMID 37110586, 2023). "Inhibition of the NF-κB signaling pathway could significantly inhibit cytokines associated with tumor immune escape, including TGF-β, IL-10 and the member of the CC chemokine subfamily (CCL-22), thereby restoring the activity of depleted T lymphocyte." (PMID 37403095, 2023). "In further support to the upregulation of key effectors for tumour surveillance, lepadin A increased synthesis of IL-6 and reduced the secretion of the immunosuppressive cytokine IL-10 in the supernatants of the co-cultures with DCs, while did not affect the levels of IL-1β and TNFα." (PMID 37779162, 2023).